MEN1 (menin 1)
Diseases named in the same sentence as MEN1 in open-access papers (continued):
Sharing a sentence is not in itself a finding about the gene and the disease.
cancer (continued). "Initial screening revealed pathogenic variants in known cancer genes, including BARD1:p.Trp91* detected in a cancer-free individual, and MEN1:p.Glu260Lys detected in a BC patient." (PMID 31681433, 2019). "These included homozygous variants calls in genes related to cancer (BRCA1, APC, MEN1), congenital malformation syndromes (TCOF1), metabolic deficiencies (FBP1, HEXA), and neurological diseases (FUS, MLC1, DMD)." (PMID 26547235, 2015). "MEN1-related aggressive and other malignant tumours of any origin were detected in 16.1% of wild-type and 33.3% of polymorphism allele-bearing patients (P = NS)." (PMID 25824098, 2015). "Notably, 11% of phenocopies had a first-degree relative with MEN1-related diseases, and 51% had a personal or family history of cancer." (PMID 41222883, 2025). "Although somatic mutations in MEN1 have not been directly linked to carcinoma conversion or metastatic transformation, we recommend early genetic testing for potential metastatic markers associated with these somatic mutations." (PMID 41293361, 2025). "MEN1 deficiency induced the nuclear accumulation of β‐Catenin and the recruitment of β‐Catenin to the MGMT promoter, which promotes MGMT transcription and leads to cancer cell growth and disruption of the TMZ response." (PMID 39041891, 2024). "About 40% of patients with MEN1 develop cancer in the digestive tract." (PMID 38730578, 2024). "MEN1-related NETs are slowly proliferating into G1-G2 malignant neoplasms." (PMID 37761922, 2023). "Our results suggest that splicing inhibitors may be therapeutically beneficial for MEN1-inactivated cancers." (PMID 37395406, 2023). "Although the MEN1 genotype–phenotype correlation is not clear, it is recommended that MEN1 mutation carriers undergo periodic imaging and endocrinological testing to facilitate early cancer detection, especially for thymic carcinoids." (PMID 36010855, 2022). "However, we observed enhanced carcinoma development in hTS/Men1+/ΔN3-8 mice as compared with Men1+/ΔN3-8 controls." (PMID 36048542, 2022). "However, seven of the dysregulated miRNAs in Men1+/− adrenals were already suggested to play active roles in tumorigenesis of different cancer types." (PMID 34285285, 2021). "We observed that expression of MEN1 was moderately negatively correlated (r = −0.22) with the mean OXPHOS gene expression in normal controls but both turned to being positively correlated (r = 0.35) as they progressed into malignant tumors." (PMID 32971831, 2020). "Currently published results strongly indicate miR-24 as a key pro-oncogenic factor, targeting MEN1 mRNA, both in MEN1 neoplasms and other non-MEN1 sporadic tumors, indicating it as a promising target for an anti-cancer therapy, aimed to restore the expression of menin." (PMID 33066578, 2020). "The majority of germline mutations in the MEN-1 gene cause the truncation or absence of the menin protein in cancer cells." (PMID 31443481, 2019). "The importance of epigenetic regulation in cancer is also underscored by the findings that a number of genes encoding critical epigenetic regulators, including MLL1, MEN1, EZH2, SETD2, JARID1C, BAF180 and UTX, have been identified as mutated in various human cancers." (PMID 21544224, 2011). "A comparison between age-matched Men1 wild-type and mutant mice revealed notable histological differences, showing a marked increase in cancer incidence in Men1+/- prostates and a significantly decreased proportion of mutant mice with normal prostate histology." (PMID 20663219, 2010). "About one-third of patients with MEN1 develop malignant tumors." (PMID 19017391, 2008). "About one-third of patients with MEN1 succumb to malignant tumors." (PMID 19017391, 2008). "MEN1 is a rare Mendelian cancer disease associated with a variety of endocrine and non-endocrine tumours." (PMID 17014705, 2006).
cancer (continued). "According to this information, miR-24-1 may represent a promising target to develop a therapeutic silencing antagomir restoring the correct expression of menin to control MEN1 tumorigenesis progression and prevent the development of cancers in the target tissues." (PMID 35205624, 2022). "Therefore, we tested whether overexpression of TS induced DNA damage in PanNETs by measuring expression of γ-H2AX in carcinoma developed in hTS/Men1–/– and Men1–/– mice." (PMID 36048542, 2022). "Neddylation has been shown to be upregulated in a multitude of cancers; with studies showing that it can directly impact the activity of NET related tumor suppressor proteins, e.g., PTEN and MEN1." (PMID 40522948, 2025). "Ectopic MEN1 expression downregulated MGMT expression and re‐sensitized cancer cells to TMZ by suppressing the nuclear accumulation and transcriptional activity of β‐Catenin." (PMID 39041891, 2024). "Overall, the global QoL score of MEN1-ZES patients was lower (64.6) than in a random sample of the general population (75.7), but higher than in a random sample of cancer patients (61.3)." (PMID 35454834, 2022). "Although our study is the largest to date to assess WNT regulators in BRAF mutant cancers, we did not have a sufficiently large enough sample size to draw conclusions as to the prognostic implications of genes that are mutated more rarely, such as MEN1 and GNG12." (PMID 32384699, 2020). "This analysis identified 11 potential cancer drivers in the WNT signaling cascade, three of which were identified by oncodriveCLUST (RNF43: p = 7.22 × 10−6, MEN1: p = 0.02, and GNG12: p = 0.012)." (PMID 32384699, 2020). "We observed a significant enrichment of MEN1 and DAXX mutations prior to LOH and genome doubling events (Bonferroni adjusted p values: MEN1 = 0.00029, DAXX = 0.00011, binomial test) when using a cutoff of 0.85 cancer cell fraction." (PMID 32345369, 2020). "The 7 CGC genes that were detected by SomInaClust only included well-known (germline) cancer genes such as BRCA1, MEN1 and NF1." (PMID 25903787, 2015). "First, to determine the efficiency of MEN1-KD upon the treatment of siMEN1#1 and siMEN1#2 in BLCA cells, we analyzed the MEN1 mRNA and menin protein expression levels in siMEN1#1 or siMEN1#2-treated cancer cells by RT-qPCR and western blotting assay." (PMID 40837414, 2025). "Additionally, heterozygous inactivation of Men1 increased the incidence of PIN, as well as both prostate adenocarcinomas and in situ carcinomas, compared to age-matched menin wild-type littermate controls." (PMID 39336822, 2024). "Furthermore, both MEN1 and PRC2 were identified as the top hits in a genome-wide screen for regulators of MHC-I expression as potential strategies to augment cancer immunotherapy." (PMID 37460547, 2023). "Importantly, a combination of highly specific and potent inhibitors of PRC2 and MEN1, which are either FDA-approved or in clinical trials to treat distinct cancer types, demonstrated remarkable efficacy in the treatment of DLBCL in xenograft study." (PMID 37460547, 2023). "We also performed TS immunoblotting and confirmed presence of hTS in carcinoma from hTS/Men1–/– but not Men1–/– mice." (PMID 36048542, 2022). "The clinical value of this data is to highlight the need for somatic testing of cancer patients with MEN1 disruptions, rather than, or at least in addition to, pedigree studies that focus on cancer pre-disposition syndromes." (PMID 32937789, 2020). "While differential loss of heterozygosity might contribute to the tissue-specific nature of MEN1 tumors, it is not sufficient to account for this phenomenon, as illustrated by the fact that forced deletion of both Men1 alleles in certain tissues does not cause cancer." (PMID 26709830, 2015). "In our cohort, no clinical or genetic data suggested MEN1-, MEN2-, or CDC73-related syndromes in the carcinoma cases, but genetic testing was not routinely performed, which is a limitation of our study." (PMID 40507262, 2025).
cancer (continued). "The true-positive rate of 64% emphasizes the patients who derive the most benefit from WB-MRI screening—those patients with LFS, MEN1, and VHL, whose cancers were found at an early, nonmetastatic stage and were treated with curative intent via surgery and systemic therapy." (PMID 40138602, 2025). "MEN1- and MEN2-syndromes may include benign (parathyroid, pituitary) or malignant tumors, which can be secretory or non-secretory, but both syndromes are defined by the presence of NET in two or more different hormonal tissues." (PMID 30817772, 2019).
endocrine disorders (13 papers, 2012 to 2025). "Multiple hyperplasia and/or adenoma of the parathyroid glands causing PHPT is the most common endocrinopathy of MEN1." (PMID 40177730, 2025). "Loss of menin expression or abnormal nuclear translocation caused by MEN1 gene mutations will cause a series of signaling pathway disorders, and then result in systemic endocrine diseases including pNETs." (PMID 36248960, 2022). "In summary, MEN1 is characterized by a more severe bone disease because of the coexistence of PHPT with other endocrinopathies that negatively affect bone mass, whereas PHPT in the context of MEN2 syndrome is either milder (MEN2A) or scarcely occurs (MEN2B)." (PMID 40177730, 2025). "pHPT occurs very early in MEN1 patients, typically between 20 and 25 years of age, and precedes the appearance of the other endocrine disorders by as much as a decade." (PMID 23259638, 2012). "In addition, even if the embryo is implanted, multiple endocrine disorders induced by MEN1 can have a long-term impact on maternal–fetal safety." (PMID 37929040, 2023). "MEN1-induced endocrine disorder rather than MEN1 mutation contributes to the ER abnormality." (PMID 37929040, 2023).
endocrine neoplasms (12 papers, 2012 to 2024). "Clinical manifestations of MEN1 are predominantly associated with classical endocrine tumors and their relative secretion products." (PMID 33312161, 2020). "Infrequently (5%) they arise in association with multiple endocrine neoplasia type 1 (MEN1), an autosomal-dominant familial tumor syndrome characterized by a high frequency of endocrine neoplasms." (PMID 22825745, 2012). "The WGS analysis led to the detection of a coding variant in the MEN1 gene in participant E. Multiple endocrine neoplasia syndrome 1 (MIM #131100) is characterised by a predisposition to many different endocrine neoplasms, in particular of the parathyroid, pancreas, and anterior pituitary gland." (PMID 34711244, 2021). "Despite the frequent occurrence of endocrine neoplasm combinations, findings so far suggest that a genetically predisposed abnormal proliferative control may exist in practically all of the mutant cells of a MEN1-affected individual." (PMID 28184288, 2017). "This genetic marker, even in the absence of overt clinical signs, points toward the potential future development of MEN1-related endocrine neoplasms." (PMID 39201946, 2024). "Typically, MEN1 is characterized by the presence of several endocrine tumors in the parathyroids, the pituitary gland and the GEP tract." (PMID 33312161, 2020). "Other endocrine tumors noted with increased frequency in MEN1 include foregut carcinoid tumors, such as thymic and bronchial carcinoid, and gastric enterochromaffin-like tumors, which each have a penetrance of 2%, 2%, and 10%, respectively by 40 years of age." (PMID 31263451, 2019). "MEN1 is clinically defined when at least two first-degree relatives have a combination of either one of the three main endocrine tumors." (PMID 28184288, 2017). "We found that DNMT1 enzymatic activity was significantly increased in the endocrine tumor tissues from MEN1 patients and Men1 KO mice as compared to normal endocrine tissues from unaffected individuals and Men1 WT control mice." (PMID 26871472, 2016). "Based on this, we examined the expression of DNMT1 in endocrine tumor tissues from MEN1 patients and Men1 KO mice." (PMID 26871472, 2016). "DNMT1 mRNA expression was significantly increased in the endocrine tumors from MEN1 patients and Men1 KO mice compared to normal by real-time RT-PCR." (PMID 26871472, 2016). "Decreased protein expression of Sox2 was also confirmed in endocrine tumors of the pancreas and parathyroids from the Men1 KO mice by IF and western blot assays." (PMID 26871472, 2016). "Xu's report showed that the protein level of DNMT1 was not regulated by menin in MEF cells, but we found the level of DNMT1 in endocrine tumors from MEN1 patients and Men1 KO mice was increased compared to normal." (PMID 26871472, 2016). "It is estimated that 10–30% of patients with a MEN1-like phenotype have no genetic mutation found in the MEN1 gene, and these patients present with endocrine neoplasms at a later age and have a similar life expectancy to that of the general population." (PMID 38038882, 2024). "Islet cell tumors are the most common endocrine gland tumor in MEN1." (PMID 35255927, 2022). "Likewise, a variable number of other endocrine and non-endocrine tumors have been described in the context of MEN1 phenotype, such as central nervous system (CNS) and cutaneous tumors, and will be subsequently summarized." (PMID 33312161, 2020). "In genetically engineered mouse models, germline targeted deletion of both copies of the Men1 gene leads to death in utero, whereas germline targeted deletion of one copy of the Men1 gene results in live mice that develop endocrine tumors similar to those in humans." (PMID 31263451, 2019). "Patients with germline inactivating mutations in MEN1 demonstrate loss of heterozygosity (LOH) in more than 90% of their tumors, though LOH involving chromosome 11q13 has also been observed in 5–50% of sporadic endocrine tumors." (PMID 31263451, 2019).
endocrine neoplasms (continued). "Her DNA had been sequenced twice via the Department of Clinical Genetics at Karolinska University Hospital (using specific Sanger sequencing and MLPA of the MEN1 gene in 2009, and whole-exome sequencing and an in silico gene list for endocrine tumours in 2015), with no pathogenic variant found." (PMID 34711244, 2021). "Multiple endocrine neoplasia type 1 syndrome (MEN1, MIM*131100) is an autosomal dominant disorder in which varying combinations of either endocrine or non-endocrine tumors may present extremely varied phenotypic clinical patterns." (PMID 28184288, 2017). "To determine if inactivation of menin increased the other three DNA methyltransferases (DNMT2, DNMT3a, and DNMT3b), we measured mRNA expression levels in the endocrine tumors from MEN1 patient samples and Men1 KO mouse models, and demonstrated no significant increase in DNMT2, DNMT3a, and DNMT3b." (PMID 26871472, 2016).
genetic diseases (10 papers, 2012 to 2024). "The expressive number of MEN1 PHPT in the present series is a consequence of a very specialized endocrinological unit dedicated to genetic diseases, leading to an increasing number of parathyroid operations." (PMID 33382714, 2020). "Therefore, although MEN1 is known to be one of the genetic diseases, it is likely that this case is a propositus case." (PMID 34384417, 2021). "MEN1 is one of the genetic diseases with autosomal dominant inheritance and its penetrance is high." (PMID 34384417, 2021). "The frequency of PNETs with hereditary disease is high in the order of MEN1, VHL, NF-1 and TSC." (PMID 22824559, 2012).
pancreas (10 papers, 2010 to 2024). "MEN1 is frequently mutated in lung NETs, and ablation of one allele of Men1 in mice accelerates lung NET development." (PMID 39336822, 2024). "Early detection of initial transformation in endocrine pancreas of MEN1 gene carriers would be beneficial for stratification of high-risk patients." (PMID 29335487, 2018).
autosomal dominant disease (7 papers, 2017 to 2024). Autosomal dominant form of disease. "MEN1: Multiple endocrine neoplasia type 1 (MEN1) is an autosomal dominant disease linked to mutations in the MEN1 gene (11q13)." (PMID 34680514, 2021). "MEN1 is an autosomal dominant hereditary disorder due to mutations in the MEN1 gene that lead to the development of tumors in the parathyroid glands, pancreas, and anterior pituitary." (PMID 30456751, 2018). "MEN1 is an autosomal dominant disease, due to germline mutations of the MEN1 gene located on chromosome 11q13." (PMID 28881068, 2017).
adenocarcinoma (3 papers, 2010 to 2025). A common cancer characterized by the presence of malignant glandular cells. "MEN1 gene detection from blood samples and positron emission tomography CT scanning have been reported as advanced methods for the diagnosis of NEC and adenocarcinoma." (PMID 24944649, 2014).
benign tumors (3 papers, 2011 to 2020). "The affected patients recorded higher serum Ca level and PTH levels than those with MEN1-associated benign tumors." (PMID 33101196, 2020). "Presently, alterations in MEN1 and CCND1 are still the main genetic alterations associated with the development of sporadic benign tumors (accounting for approximately 30% of the cases)." (PMID 22567348, 2011).
infection (2 papers, 2022 to 2025). The state of being infected such as from the introduction of a foreign agent such as serum, vaccine, antigenic substance or organism. "For MEN1 KO, we repeated the NT and MEN1 gRNA infection with extended doxycycline treatment (from 2 to 4 days) to improve KO efficiency." (PMID 40897805, 2025).
epithelial neoplasm (1 paper, 2025). A benign or malignant neoplasm that arises from and is composed of epithelial cells.
hematologic malignancies (1 paper, 2023). "In this analysis, seven of eight malignancies with the highest dependency on MEN1 belong to the group of hematologic malignancies." (PMID 38003662, 2023).
MEN1 also shares sentences with these, for which no sentence is quoted: multiple endocrine neoplasia type 2A (9 papers); neurofibromatosis (7); hereditary leiomyomatosis (6); hereditary cancer syndrome (5); pancreatic gastrinoma (5); pituitary disease (5); cholangiocarcinoma (4); Familial adenomatous polyposis (4); Lynch syndrome (4); renal cell carcinoma (4); cardiovascular disease (3); CNS tumors (3); gastric tumor (3); neonatal severe hyperparathyroidism (3); non-small cell lung carcinoma (3); osteosarcoma (3); pancreatitis (3); angioma (2); colon cancer (2); esophageal disease (2); esophageal leiomyoma (2); Familial hypocalciuric hypercalcemia type 1 (2); Familial Isolated Pituitary Adenoma syndrome (2); Gorlin syndrome (2); Hyperinsulinemia (2); hyperinsulinemic hypoglycemia (2); hyperprolactinemia (2); hyperthyroidism (2); hypogonadism (2); kidney cancer (2).
A further 131 diseases each share a sentence with MEN1 in 2 papers or fewer.